NRAS (NRAS proto-oncogene, GTPase)
Diseases named in the same sentence as NRAS in open-access papers (continued):
Sharing a sentence is not in itself a finding about the gene and the disease.
cancer (continued). "The RAS oncogene, which can exist in either of the HRAS, KRAS, or NRAS isoforms, is found mutated in approximately 30% of all human cancers and produces aggressive, treatment resistant tumors." (PMID 27330862, 2016). "The 3 human RAS genes (HRAS, KRAS, and NRAS) are among the most prevalent drivers of human cancer, with KRAS being mutated in 20-25% of all human tumors and up to 90% in certain cancer types, e.g. pancreatic cancer." (PMID 26028667, 2015). "NRAS subtype: mutations in NRAS, playing a crucial role in initiation and promotion of many human cancers, with increased levels of phospho-ERK expression, associated with possible activation of PI3K-AKT pathway." (PMID 26322273, 2015). "Subsequently, in 1994, cancer-specific DNA mutations in NRAS (myelodysplastic syndrome 7) and KRAS (pancreatic cancer 8) were detected in the blood of cancer patients." (PMID 26119132, 2015). "The association of low expression of the cluster and RAS mutation was particularly strong in the case of NRAS mutation where 76.9% of these cancers were in group D and over 90% of these tumors clustered in the two lowest expression groups (B and D)." (PMID 25949894, 2015). "We found recurrent mutations in 4 cancer genes and delineated that NRAS, KRAS and ATM mutations are distributed in a mutually exclusive fashion." (PMID 25115387, 2014). "The three RAS oncogenes (HRAS, KRAS and NRAS) are mutationally activated in ~30% of all cancers and are implicated in promoting multiple aspects of the malignant cancer phenotype." (PMID 19682393, 2009). "Specifically, the Ras family of GTPases is known for regulating actin cytoskeleton dynamics and cell migration, largely through the Ras subfamily of GTPases (HRAS, KRAS, NRAS), which have been found to be mutated in individuals with cancer and drive cancer metastasis." (PMID 41200767, 2025). "Although these HRAS p.G12C and NRAS p.G12C mutations are relatively rare in patients with cancer, these findings suggest that glecirasib could offer new treatment options for these patient populations." (PMID 40304209, 2025). "Studies on the RAS gene family—KRAS, HRAS, and NRAS—have revealed the pivotal role of KRAS mutations in various cancers despite their relatively low frequency in breast cancer, emphasizing the untapped potential for precision treatments targeting this mutation." (PMID 40236954, 2025). "Somatic mutations in the KRAS, HRAS, and NRAS genes are often presented in different cancers." (PMID 41438146, 2025). "Therefore, the present study aimed to characterize plasmid-HTVI models overexpressing active forms of AKT, c-Met and NRas combined with TAA as a liver injury agent to elucidate pathogenic pathways associated with cancer progression in these models." (PMID 39254423, 2024). "Directly targeting the RAS oncoprotein itself may exploit the high degree of oncogene addiction of KRASG12X (and NRAS)-mutated cancer cells to a greater degree than targeting upstream and downstream signalling proteins (such as SHP2, MEK1/2 and ERK1/2)." (PMID 38589574, 2024). "However, we still believe that analyzing all available patients with NRAS mutations in the TCGA database is valuable in revealing the potential for using microRNA to treat NRAS-mutation-driven cancers." (PMID 37083947, 2023). "The rates of NRAS mutation in these cancer types are 20%, 0.9%, and 15%, respectively." (PMID 37083947, 2023). "NRAS mutation was observed more in well (5.3%) than in moderately (1.8%) differentiated carcinoma." (PMID 37277698, 2023). "KRAS and HRAS were initially identified in cancer cells as the human orthologs of those proto-oncogenes responsible for the initiation of sarcoma in rats infected with two cancer-causing viruses, while NRAS was discovered shortly after by homology with KRAS and HRAS." (PMID 35234863, 2022). "Metabolic reprogramming is considered a novel target to control cancer; however, NRAS-oncogene contribution to this cancer hallmark is mostly unknown." (PMID 36402789, 2022).
cancer (continued). "Treatment of cancer cells with known drugs could shed further light on the underlying mechanisms for the association of NRas and BRAF in mutual clusters." (PMID 36304112, 2022). "Unlike KRAS G12C–selective inhibitors, targeted inhibition of BCL6 might be effective in the majority of KRAS-mutant cancer subtypes and even in tumors harboring NRAS mutations." (PMID 36377663, 2022). "Thus, it is essential to further investigate the molecular mechanism of NRAS mutation-mediated cancers to look for an efficient pathway of drug design for the treatment of human cancers." (PMID 36080363, 2022). "NRAS mutations constitutively activate cell proliferation signaling in malignant tumors." (PMID 36358254, 2022). "Furthermore, considering hallmark types and numbers, MAPK3 and NRAS showed the same profile, and they were involved in 9 out of 10 cancer hallmarks." (PMID 36304266, 2022). "The G12C mutation is a common mutation in the Ras proto-oncogenes (HRAS, KRAS, and NRAS) and, therefore, might be a suitable mutation to target various types of cancer and their causes." (PMID 35062725, 2021). "Thus, circPVT1 directly affects the level of functional NRAS protein and subsequently drives cancer hallmark phenotypes in cells." (PMID 33907219, 2021). "Members of the rat sarcoma (RAS) oncogene family, including Kirsten-RAS (KRAS), Harvey-RAS (HRAS), and neuroblastoma-RAS (NRAS), exhibit the highest mutation frequency in human cancers, with associated mutations being identified in approximately 30% of all cancers." (PMID 34512755, 2021). "In mutant KRas-driven cancer cells, the “open conformation” dominantly results from the activated KRas due to the “open conformation” accounting for more partition in mutated KRas than in wild-type HRas and NRas." (PMID 35069209, 2021). "NRAS mutations were detected in 8.9% of the cases, being present in benign and malignant tumours, with a higher frequency in the FTA (35%—6 cases), 18% in CV-PTC (3 cases), 12% in FTC, FV-PTC and OV-PTC (2 cases each), and 6% in PDTC (1 case) and in the single distant metastasis analysed." (PMID 32659948, 2020). "The mutation-specific effects, if they are functional, may unbalance the distribution of each driver mutation in different cancer types, such as NRAS Q61R, which is almost exclusively observed in melanoma." (PMID 31925297, 2020). "Among the three paralogs, KRAS is the most frequently mutated protein in cancers, followed by NRAS." (PMID 33187149, 2020). "The intersection of differentially expressed genes (DEG) and our list of candidate genes, resulted in 12 elements including cancer associated genes (NRAS, MYC, and VEGFA), circadian drug targets (SOD2 and CES2) and core-clock and ECCN genes (AHR, CREB1, CSNK2A1, NFIL, NPAS2, NR1D1, and PER3)." (PMID 32295075, 2020). "KRAS has the highest mutation rate compared to HRAS and NRAS in various types of cancers." (PMID 30971271, 2019). "NRAS is a member of a family of oncoproteins that are commonly mutated in cancer." (PMID 31080553, 2019). "RAS genes (HRAS, KRAS, and NRAS) are the most frequently mutated gene family in cancer." (PMID 31681587, 2019). "Moreover, NRAS mutations are postulated to promote the malignant behavior of cancer cells in advanced colorectal malignancies; the results of both in vitro and animal studies suggest that this process can be reverted by silencing mutated codons." (PMID 29682098, 2018). "Among the RNA targets that displayed a polysomal shift are mRNAs encoding proteins related to cancer, such as NRAS, the Ras-related protein R-Ras2, and those related to cell cycle, such as CDC27, the retinoblastoma binding protein RBBP8, and retinoblastoma-like 1 (RBL1)." (PMID 24842991, 2014).
cancer (continued). "NRAS is a known cancer driver oncogene and mutations may lead to dysregulation of the Ras pathway." (PMID 39149342, 2024). "Notably, mutation of the NRAS gene, which is linked to cell division in cancer, was found to be the variable most correlated with CPP uptake, followed closely by mutation of IDH1, which is associated with the expression of isocitrate dehydrogenase 1, a key player in the Krebs Cycle." (PMID 38365724, 2024). "In particular, the KRAS rs8720 and NRAS rs14804 SNPs play an important role in these patients, especially where certain genotypes are associated with a higher risk of disease progression and more aggressive clinical features, including lymph node spread and advanced cancer stages." (PMID 39867023, 2024). "Although sotorasib was considered KRAS G12C specific and is FDA-approved for KRAS G12C mediated cancers only, studies have indicated it may be suitable for other NRAS or HRAS G12C-mutated cancer, delivering potential to revolutionise the way in which the drug can be used." (PMID 39372214, 2024). "Additionally, it also has been reported that YAP may be associated with resistance to cancer target therapy in cancer cells harboring NRAS, KRAS, or BRAF mutations 22-25." (PMID 36619222, 2023). "Interestingly, JNK inhibitor co-treatment could enhance the cancer cytotoxic effect of the ferroptosis inducers in NRAS and KRAS mutation-harboring cells (HT-1080 and MIA PaCa-2)." (PMID 36232313, 2022). "Interestingly, NRAS is the main mutated isoform of RAS in these two cancers." (PMID 36163168, 2022). "Therefore, targeting PLCB1 and DESC1 could be potential strategies for inhibiting the resistance to MEK1/2 inhibition in certain cancers with NRAS or BRAF mutations." (PMID 34064422, 2021). "The top twenty differentially expressed genes in pathways in cancer (PC) include the well-known oncogene NRAS, the inhibitor of apoptosis BIRC3/cIAP2, and WNT7B, a component of the WNT/β-catenin pathway." (PMID 41467516, 2026). "Therapeutic targeting of the oncogenic NRAS protein, which is constitutively activated in human cancers, with small molecules is a promising yet challenging anticancer strategy." (PMID 42212085, 2026). "Orthologues of RAS were originally discovered in cancer-causing viruses in rats, leading to the identification of three endogenous human RAS genes, NRAS, KRAS, and HRAS." (PMID 41535418, 2026). "Specific gene mutations, such as KRAS, NRAS, and BRAF, are known to play a crucial role in the propagation of both cancers." (PMID 40447784, 2025). "In KRAS- or NRAS-mutant cancers, FTIs failed because the tumor simply utilized geranylgeranyltransferase to prenylate RAS instead." (PMID 40335986, 2025). "The first report demonstrated that ARAF overexpression reduces sensitivity to LXH254 in K/NRAS-mutant cancers." (PMID 41023593, 2025). "As a result, ~19% of cancer patients harbor a RAS mutation, with KRAS accounting for 75% of RAS-mutant cancers, while NRAS (17%) and HRAS (7%) are associated with a smaller subset." (PMID 40801144, 2025). "One cancer had a class 3 mutation (G466V), two atypical KRAS mutations (V14L and D33E), and an NRAS mutation (G12V)." (PMID 39751654, 2025). "KRAS is central in metabolic regulation in pancreatic cancer models, while HRAS and NRAS exhibit distinct functions in other cancer types." (PMID 40906088, 2025).
cancer (continued). "Mutations in pathway-related genes, such as KRAS, NRAS, BRAF, and PIK3CA, influence treatment responses and serve as key prognostic indicators in cancer treatment." (PMID 40279317, 2025). "Mutations in KRAS, NRAS, and HRAS are among the most frequent oncogenic alterations in human cancers." (PMID 41196374, 2025). "Among the RAS oncogene family, which includes KRAS, HRAS, and NRAS, KRAS is the most frequently mutated, accounting for ∼30% of all RAS-driven cancers, while HRAS and NRAS mutations are less common, occurring in ∼8% and ∼3% of cases, respectively." (PMID 40563459, 2025). "The three Ras genes (KRAS, NRAS, and HRAS) are frequently mutated in cancer (11%, 3%, and 1% of cancers in the US, respectively), and the corresponding proteins are active when localized to the membrane." (PMID 39995872, 2025). "This transduction process produced the viral oncogenes HRAS and KRAS, which were later shown, along with NRAS, to play key roles in human cancer." (PMID 40906088, 2025). "Inhibiting NRAS localization to the plasma membrane (PM) represents a promising strategy for cancer therapy, as its oncogenic signaling relies on PM localization." (PMID 40091521, 2025). "We investigated the frequency of RAS mutations (KRAS, NRAS, HRAS) in different cancer types using the C-CAT database, a Japanese national cancer genome database." (PMID 40970755, 2025). "This study highlights the feasibility of selectively targeting NRAS as a potential therapeutic avenue for NRAS-mutant cancers." (PMID 39379700, 2024). "On the other hand, Reactome enrichment analysis identified RHO GTPase associated signaling pathway to be the main pathway downregulated upon BAY 11-7082 treatment in NRAS mutant cancer cell." (PMID 38982514, 2024). "Targeting NRAS localization to the plasma membrane (PM) is a promising strategy for cancer therapy, as its signaling requires PM localization." (PMID 38317235, 2024). "Combined analysis of n = 1079 human cancer cell lines (> 25 lineages) showed that activating mutations in KRAS, NRAS and HRAS correlate significantly with increased c-RAF gene dependency vs. wild-type RAS." (PMID 38637546, 2024). "Mutations of RAS proto-oncogenes (HRAS, NRAS, KRAS4A, and KRAS4B) are among the most common genetic alterations observed in human cancer." (PMID 38858602, 2024). "LY3009120 or combinations with CDK4/6-inhibitors such as abemaciclib have shown stronger anti-tumor effects with BRAF-mutant cancer cells than cancer cell lines with various NRAS genotypes." (PMID 38397192, 2024). "Of the oncogenic mutations in the RAS family, the KRAS locus is the most often affected with a relatively higher prevalence in about 30% of cancerous tumors, while the HRAS and NRAS locus mutations are present in a modest 8% and 3%, respectively." (PMID 39184150, 2024). "These DNA targets consisted of multiple KRAS, BRAF and NRAS SNPs, which are commonly used as cancer markers for the detection and characterization of various cancer types, for example, in liquid biopsies." (PMID 39201654, 2024). "The molecular genetic somatic mutation research in cancer plays an essential role and the presence of mutated genes that belong to the Ras subfamily (e.g., KRAS, NRAS, HRAS) allows for the detection of several cancer types." (PMID 38539435, 2024). "Our study identifies BAY 11-7082 to be an efficacious inhibitor for treating RAS oncogene (HRAS, KRAS, and NRAS) mutant cancer cells." (PMID 38982514, 2024). "For decades, pervasive dogma in the field was that all mutations in all three cancer-relevant RAS isoforms (KRAS, HRAS, and NRAS) were functionally equivalent." (PMID 38800401, 2024). "Four isoforms of the RAS protein are found in humans: HRAS, NRAS, KRAS4A, and KRAS4B, with RAS mutations detected in 19% of cancer patients (75% in KRAS, 17% in NRAS, and 7% in HRAS)." (PMID 39301544, 2024).
cancer (continued). "Mutations in the rat sarcoma viral (RAS) oncogene family, specifically KRAS, HRAS, and NRAS, are among the most prevalent among human tumorigenesis found in 30% of all cancer types included." (PMID 39184150, 2024). "KRAS and NRAS, two GTPase proteins encoded by RAS family member genes, play crucial roles in cancer development." (PMID 39624124, 2024). "The RAS GTPases are the most frequently mutated oncogene family in human cancers with RAS isoforms (HRAS, KRAS, and NRAS) regulating critical intracellular signaling cascades that control cell proliferation and survival." (PMID 39379700, 2024). "H/K/NRAS are highly studied, attributed to their role in cancer, while research on many alternative RAS GTPases remains limited." (PMID 39009833, 2024). "Remarkably, depleting GOLGA7 effectively inhibits cell proliferation in multiple NRAS-mutant cancer cell lines and attenuates NRASG12D-induced oncogenic transformation in vivo." (PMID 38317235, 2024). "ACA-28 and its lead compound ACAGT-007a were shown to induce apoptosis in cancer cell lines with different oncogenic mutations, ranging from HER2, BRAF, NRAS, and KRAS." (PMID 38500550, 2024). "Three rat sarcoma (RAS) gene isoforms, KRAS, NRAS, and HRAS, constitute the most mutated family of small GTPases in cancer." (PMID 37662925, 2023). "HRAS, referred to as oncogenic RAS with NRAS and KRAS, is one of the most frequently mutated driver proto-oncogenes in cancer." (PMID 36906552, 2023). "The lack of association in patients with BRAF mutant cancers was unlikely to be due to the small numbers of samples (n = 120) since we observed this effect in a much smaller group with NRAS mutant cancers (n = 44)." (PMID 36790221, 2023). "Considering the Afirma Gene Expression Classifier and ThyroSeq genomic classifier are not yet available in China and are expensive, 5 of the most common cancer-associated somatic mutations (BRAF, HRAS, NRAS, KRAS and TERT) were offered in our hospital." (PMID 36737779, 2023). "The RAS (KRAS, NRAS, HRAS)-RAF (ARAF, BRAF, RAF1)-MEK (MAP2K1/2)-ERK (MAPK1/3) pathway is altered in ~40% of all human cancers, mainly through oncogenic mutations in RAS (32%) and the downstream effector BRAF (~10%)." (PMID 37370689, 2023). "RAS mutation is the most frequent oncogenic alteration in human cancers, and KRAS is the most frequently mutated followed by NRAS." (PMID 36583506, 2023). "Of these genes, GNAQ, GNAS, and JAK2 are associated with cell growth-related factors, whereas NRAS, IDH2, and CTNNB1 are cancer-related genes." (PMID 36780540, 2023). "We showed that miR-708 directly suppressed NRAS expression and this NRAS depletion led to the reduced proliferation of cancer cells through subsequent oncogenic signaling inhibition." (PMID 37083947, 2023). "Given that ERK and AKT are both downstream effectors of RAS, our results were intriguing as their activation was differentially regulated when NRAS was suppressed by miR-708 in different cancer cell lines." (PMID 37083947, 2023). "HRAS-mutant cancers had a higher frequency of co-altered mutations (48.8%) in MAPK, PI3K, or RTK pathways genes compared to KRAS- and NRAS-mutant cancers (41.4% and 38.4%, respectively; p < 0.05)." (PMID 37503077, 2023). "NRAS and HRAS are proto-oncogenes involved in cell division; thus, their mutations can lead to uncontrolled proliferation, a feature of cancer cells." (PMID 38137511, 2023). "Taken together, these findings demonstrate that miR-708 negatively regulates NRAS expression and subsequently suppresses one of the main effector pathways, to decelerate cancer cell proliferation, in the three cell lines we examined." (PMID 37083947, 2023). "The success of miR-708 suppressing NRAS is proof of the concept that using microRNA to antagonize the “undruggable” cancer target." (PMID 37083947, 2023).